MTOR (mechanistic target of rapamycin kinase)
Diseases named in the same sentence as MTOR in open-access papers (continued):
Sharing a sentence is not in itself a finding about the gene and the disease.
tumor (continued). "They showed that rapamycin, an mTOR pathway inhibitor, combined with miR-34, a tumor-suppressive micro-RNA, associated with the regulation of stem-like cells in solid tumors, could overcome CSC-associated radioresistance." (PMID 37046623, 2023). "If these conclusions can be generalised, pulsatile treatments alternating tyrosine kinase and mTOR inhibitors could provide a promising strategy to hamper tumour growth, reducing the risk of disease ‘rebound’." (PMID 36697438, 2023). "Also, the increase of ROS in tumor cells is positively associated with the downstream PI3K/Akt/mTOR signal transduction pathway." (PMID 36765353, 2023). "The survival and function of tumor-associated immune cells require mTOR." (PMID 37064872, 2023). "Therefore, blocking the Akt/mTOR pathway has been linked to reduced tumor growth and increased patient survival." (PMID 37190229, 2023). "On the other hand, ESCO2 was shown to regulate mTOR in tumor cells; therefore, STAT1 may also be associated with ESCO2’s molecular activity." (PMID 37968576, 2023). "Arginine-activated mTOR is implicated in tumor cell growth and proliferation but also epigenetic reprogramming; mTOR promotes acetyl-CoA synthesis through the activation of ATP citrate synthase (ACLY) and Acyl-coA synthetase short-chain family member 1–2 (ACSS 1–2)." (PMID 37568713, 2023). "We, therefore, aimed to develop an effective and safe strategy targeting these anti-apoptotic proteins with DT2216 (our platelet-sparing BCL-XL degrader) and AZD8055 (an mTOR inhibitor) to avoid associated on-target toxicities while synergistically optimizing tumor response." (PMID 36588105, 2023). "The activity of the mTOR protein seems to play a significant role in tumor aggressiveness and might be a risk factor for metastatic potential." (PMID 36980552, 2023). "A unique tumor-associated vasculature is activated through a variety of mechanisms, including an increased level of reactive oxygen spices (ROS) and activation of mechanistic target of rapamycin (mTOR) pathway." (PMID 37849740, 2023). "In addition to a significant increase in the MSI-H group (p = 0.047), the mutation frequency of MTOR differed according to tumor location." (PMID 35883111, 2022). "Loss of DAB2IP could enhance tumor growth and resistance to mTOR-targeted therapies and ionizing radiation in RCC." (PMID 35562342, 2022). "Interestingly, mTOR regulates T cells, tumor-associated macrophages (TAMs), and antigen-presenting cells and promotes their development and activation." (PMID 36428613, 2022). "The TFE3 protein could inhibit the p21-mediated pRB pathway and activate the P13K/AKT/mTOR pathway, thereby leading to excessive proliferation tumor cells and ultimately causing progression of the tumors." (PMID 36276115, 2022). "The increased tumor burden was associated with aberrant p62 mutant aggregates and Nrf2 overactivation, but not with other protumorigenic functions of p62 through regulation of fibrosis, cMYC expression or mTOR activity." (PMID 35626041, 2022). "The mTOR protein, which is encoded by the mTOR gene, belongs to a serine-threonine kinase that controls cell responses to stressors such as growth factors, nutrient deprivation, and DNA damage and regulates tumor growth, survival, and metabolic signaling." (PMID 35402264, 2022). "Thus, mTOR plays a causal yet paradoxical role in regulating chemotherapeutic response; inhibition of the mTOR pathway, while suppressing tumor expansion, facilitates the development of a reversible drug-tolerant senescence state." (PMID 36396656, 2022).
tumor (continued). "However, only WT cells were able to partially rescue mTOR activity when lactate was included in the culture, reflecting the loss of mTOR activity specifically in tumor-infiltrating MPC1 KO CD8+ T cells in vivo." (PMID 35452600, 2022). "Currently, CAR-T immunotherapy targeting IL13Ra2 are being research as the target is a commonly expressed membrane-bound protein in over three-quarters of GBMs and is associated with activating the mTOR (mammalian target of rapamycin) pathway, which favours tumour growth." (PMID 36299480, 2022). "This conclusion is also applicable for samples with positive TRPC7 mRNA abundancy (89.0%), meaning that in any case of positive signal for TRPC3 or TRPC7 expression in a given tumor, the tumor cells frequently possesses the prominent mTOR pathway activating mutation." (PMID 35330477, 2022). "We activate Raf/MEK/ERK and PBK/Akt/mTOR pathways through autophosphorylation of receptor tyrosine kinases, causing uncontrolled cell division, proliferation, and transformation, stimulating neovascularization, and promoting tumor growth and metastasis." (PMID 35035522, 2022). "Furthermore, the expression of FAM72A and mTOR was significantly associated with the abundance of some tumor-infiltrating immune cells, especially CD4+ T cells." (PMID 36483027, 2022). "Indeed, in presence of mTOR pathway mutations, we observed pathway enrichment involved in anti-tumor immunity in tumors, as well as enhanced antigen presentation and increased infiltration in immune effector cells." (PMID 35642038, 2022). "Dysregulation and mutation of the mTOR pathway can contribute to tumor initiation and progression." (PMID 35326708, 2022). "Furthermore, a possible role of mTOR inhibitors in preventing and/or reversing tumor-associated cachexia through restoration of autophagy or reduction of IL-6 levels has also been demonstrated." (PMID 35805003, 2022). "In the present study, we found significant association only between p-mTOR extent score and pattern of tumour invasion (when grouped I + II vs III + IV) and between p-mTOR intensity score expression and number of mitosis, although in a different association direction than the expected." (PMID 35883491, 2022). "The PI3K/AKT/mTOR pathway is one obvious target in PTEN-deficient tumours." (PMID 35326717, 2022). "The mTOR mutation E2419K also contributes to tumor resistance to EGFR-TKI." (PMID 35684449, 2022). "Furthermore, ATM‐associated DNA damage response cooperates with MAPK and mTOR signaling pathways to control citrate‐induced tumor cell growth arrest and senescence." (PMID 34747157, 2022). "At mechanistic level, tumor growth impairment was coupled with a decrease in cyclin B1, Rb, Foxm1, Plk1 and phosphorylation of the ribosomal protein S6, a protein phosphorylated by the mTOR pathway and tightly associated with cell cycle progression." (PMID 35712501, 2022). "This suggests the dual role of mTOR in tumor angiogenesis; therefore, targeted mTOR strategies for attenuating tumor angiogenesis should be based on the further exploration of the underlying mechanism and the optimization of the anti-tumor function." (PMID 35327584, 2022). "The CTNNB1 mutation and high mTOR activity is compatible with SNU398 originating from a R3 tumor." (PMID 36309506, 2022). "High MTOR expression was correlated with high tumor mutation burden (TMB) and several TIICs." (PMID 35883111, 2022). "Taken together, these data indicate that the anti-tumor activity of dezocine may be associated with the inhibition of the Akt/mTOR signaling pathway." (PMID 36568517, 2022).
tumor (continued). "Additionally, combined with the molecular characterization, we noticed that dA-AL-I detection was more likely to be correlated with a higher frequency of mTOR mutations in tumor samples." (PMID 35071023, 2021). "Reasons other than body fatness or excessive energy intake, such as mutations, may increase p-mTOR expression because tumor growth is autonomous." (PMID 34330319, 2021). "In our study, we also found a correlation between MTOR mutations and tumor recurrence." (PMID 33407469, 2021). "Among these pathways, the AMPK/mTOR pathway is closely associated with tumour metabolism." (PMID 34926459, 2021). "However, evidence shows that mTOR deregulation is implicated in tumorigenesis and tumor progression." (PMID 34446793, 2021). "Several studies indicate that activation and dysregulation of the serine/threonine kinase mammalian target of rapamycin (mTOR) are associated with tumorigenesis but also processes like tumor growth, metastasis, and drug resistance in various tumor entities (Popova and Jücker 2021)." (PMID 35096817, 2021). "Metformin is able to affect the mTOR signaling by different pathways, and evidence has been provided that a combined treatment with metformin and everolimus may reduce the risk of tumor cell escape from therapy." (PMID 34884872, 2021). "Thus, taxifolin associated inhibition of tumor growth was correlated with inhibition of mTOR and PI3K pathway activity." (PMID 34462635, 2021). "However, it emphasized on TFEB-mediated mitochondrial regulation and the association between Drp-1 and mTOR, thus ignoring the positive effect of Lut in inhibiting Dox-induced cardiotoxicity in cardiomyocytes and tumor cells." (PMID 34722681, 2021). "Inhibition of mTOR activity induced by RAPA may cause an increase in autophagy flux in tumor cells and consequently contribute to a reduction in tumor growth." (PMID 34071600, 2021). "Indeed, simultaneously reduced PTEN and high PI3K/mTOR expressions were associated with lymphatic invasion (p = 0.01), advanced tumor stage (p = 0.01), distant metastases (p = 0.03), shorter DFI (p = 0.04), and shorter OS (p = 0.05) in univariate analysis." (PMID 34833123, 2021). "Therefore, the proper selection of tumor types as well as driver mutations that oncogenically activate the PI3K/Akt/mTOR pathway is essential in achieving the full potential of PI3K/Akt/mTOR inhibitors." (PMID 33723724, 2021). "We thus proposed that the tumor-suppressing properties of DLEU2L may be associated with the inactivation of the AKT/mTOR signaling pathway to impair GEM resistance." (PMID 33968986, 2021). "Thus, anti-tumor effects of LQ were also associated with the inactivation of PI3K/AKT/mTOR pathway and autophagy-related apoptosis in vivo." (PMID 34488535, 2021). "The activation of mTOR causes an accelerated tumor cell cycle, shortened G1 phase duration, rapid cell proliferation, and increased secretion of on coproteins, and this promotes tumor development." (PMID 34178945, 2021). "mTOR might be a potential target strategy for ESCC treatment in the future because it is highly expressed in many human ESCC tumor tissues and is associated with various clinical characteristics." (PMID 35155187, 2021). "The autophagy of tumor cells is mainly associated with the mammalian target of rapamycin (mTOR)." (PMID 33869189, 2021). "Specifically, PD-L1 could enhance the glycolysis of tumor cells by association with some signaling proteins, such as mTOR." (PMID 34068143, 2021). "Notably, the inhibition of PI3K/AKT/mTOR pathway in allograft-derived nodules specifically causes the loss of tumor stem cells, strongly suggesting a role of this pathway in MB resistance and relapse." (PMID 34395258, 2021). "Of these factors, PI3K/AKT/mTOR signaling pathway is increasingly believed to play a major role, as it is the most commonly activated signaling pathway in human malignancies, implicated in both tumor progression and resistance." (PMID 34832087, 2021).
tumor (continued). "Several preclinical studies using genetically engineered NF1 mouse models or established human tumor cell lines have demonstrated that mTOR overactivation underlies tumor proliferation in NF1, underpinning the therapeutic potential of rapamycin and its analogs." (PMID 34576341, 2021). "Second, PI3K/AKT/mTOR mutational activation results in increased tumor proliferation but could also be important in HNSCC immune evasion due to the downregulation of components in the antigen-processing machinery." (PMID 35047999, 2021). "Defective genes that impact PI3K-Akt-mTOR signaling could weaken the tumor cell and enhance susceptibility to chemotherapeutic drugs." (PMID 33909629, 2021). "PTEN is known to control DNA repair, cell proliferation and survival, guards the genome against structural and numerical chromosome instability and is an essential tumor suppressor gene that encodes a phosphatase protein that antagonizes the PI3K/AKT/mTOR antiapoptotic pathway." (PMID 31920463, 2020). "However, relative abundance of a fraction of cells harboring PIK3CA (H665D) and mTOR (V1795M) mutations, which are predicted as likely functional mutations, declined substantially in the lung metastasis compared to the primary tumor." (PMID 31953485, 2020). "All this points to the fact, that tumor cells are more susceptible to mTOR inhibition." (PMID 32373532, 2020). "Activation of mammalian target of rapamycin (mTOR) and loss of tumor suppressors like LKB1 may activate HIF-1 by enhancing HIF-1α protein synthesis." (PMID 32531951, 2020). "Furthermore, a role for mTOR inhibitors in preventing and/or reversing tumour-associated cachexia through restoration of autophagy or reduction of IL-6 levels has been previously shown." (PMID 32577163, 2020). "In this part, we investigated whether the expression change of ER caused by apigenin could inhibit the PI3K/Akt/mTOR signaling pathway, thereby suppressing tumor development." (PMID 32340124, 2020). "Second, in this study, we selected seven variants of two genes in the AKT/mTOR tumor network." (PMID 33247671, 2020). "Then, we put forward the hypothesis that the tumor-promoting effect of FOXK1 might be associated with the Akt/mTOR signaling pathway." (PMID 32363163, 2020). "Furthermore, blockade of mTOR by AZD8055 hampered the tumor-promoting effect from the loss of SNHG3." (PMID 32284745, 2020). "AMP-activated protein kinase (AMPK), as a stress-response molecule, is closely associated with tumor-suppressive functions by suppressing the activity of Akt and downstream mammalian target of rapamycin (mTOR), leading to cell growth inhibition and cell cycle arrest." (PMID 33520990, 2020). "Specifically, whereas subtype-1 tumours show upregulation of mTOR signalling associated kinases (among others, MTOR-pS2448, GSKB-pS21-S9, and PDK-pS241), subtype-2 tumours display upregulation of cell cycle associated kinases (among others, CDK1-pY15, p27-pT158, and p27-pT198)." (PMID 31988390, 2020). "To identify whether mTOR activity is crucial for PDP1-mediated tumor cell proliferation, we transfected a plasmid encoding the protein with a mutation that leads to constitutive activation of mTOR in PDAC cells with PDP1 knockdown." (PMID 32782783, 2020). "Indeed, a study using a tumor-bearing mouse model showed that blocking PD-L1 on tumor surface suppressed intracellular glycolysis by inhibition of mTOR activity, suggesting an association between the PD-L1 and mTOR signaling pathways." (PMID 32458996, 2020). "M2 macrophages, instead, are activated by anti-inflammatory cytokines (interleukine-4 and interleukine-10) and the PI3K/AKT/mTOR pathway, and exert immunosuppressive effects associated with enhanced angiogenesis and tumor progression, pushing OTS cells in stemness status." (PMID 32878021, 2020). "Therefore, by balancing the benefit and potential risk of adverse events, an mTOR inhibitor regimen can be selectively recommended to patients at a high risk of tumour recurrence." (PMID 33053849, 2020).
tumor (continued). "In GC and CRC, activation of mTOR appears to cause tumor progression and poor patient survival." (PMID 32626705, 2020). "Additionally, targeting the mTOR pathway by rapamycin has also been demonstrated to have an effect on NF1-associated tumours in an engineered mouse model of NF1." (PMID 32102484, 2020). "Importantly, mTOR inhibitors also reduced staining level of tumor-associated TF protein, which was consistent with our in vitro results." (PMID 32923403, 2020). "In addition to tumor suppression via apoptosis, the mTOR signaling blockade is also associated with enhanced autophagy in HCC cells." (PMID 31293977, 2019). "Loss of 4E-BPs in tumor cells results in the resistance to mTOR inhibition." (PMID 31277692, 2019). "While tumor cells with mutations in the kinase domain are still responsive to rapalogs, mutations in the kinase domain of mTOR, such as M2327I, S2215Y, L2230V, E2388Q, and V2046A, may be responsible for the resistance to the ATP-competitive inhibitor MLN0128." (PMID 31277692, 2019). "However, in the thyroid cancer extraordinary responder case study, the tumor gained resistance to rapalog treatment as it acquired a mutation in mTOR, which prevented the binding of the rapalog, as well as a nonsense mutation in TSC2." (PMID 30764584, 2019). "Therefore, the inhibition of Akt and PDK1 is considered a prominent strategy in tumor settings associated with hyperactivation of the PI3K/mTOR pathway." (PMID 31683659, 2019). "The PI3K/AKT/mTOR pathway is a relevant pathway that regulates intracellular signaling in different biological process, as apoptosis, differentiation, cell proliferation, and autophagy; additionally, it has been implicated in tumor growth and metastasis." (PMID 31547522, 2019). "Our results suggest that the activation of the Akt/ mTOR pathway might participate to the cell proliferation associated with tumor growth." (PMID 30897085, 2019). "Loss of function of the NF1 gene causes mTOR activation and tumour development." (PMID 31443481, 2019). "Another study demonstrated that genetic variations at important loci within the PI3K/PTEN/AKT/mTOR pathway could be used to identify patients with high risk of tumor recurrence or second primary tumor occurrence." (PMID 31756179, 2019). "The most compelling evidence that mutations activating the mTOR pathway correlate with the epithelioid/SEGA-like morphology was revealed by the integrated analysis of the 1st patient’s tumor, in which two distinct temporal, morphological and genetic surgical samples were available for analysis." (PMID 31258848, 2019). "This suggests that the activation of the Akt/ mTOR pathway might participate to the cell proliferation associated with tumor growth." (PMID 30897085, 2019). "Beyond those important tumor-associated pathways, the other significant pathways were also closely related to the tumor occurrence and development, such as mTOR signaling, Gap junction signaling, OC signaling, protein ubiquitination pathway, and PPAR-α/RXRα activation." (PMID 31258820, 2019). "Furthermore, the inhibition of the mTOR pathway by temsirolimus is in line with reversed tumor-associated angiogenesis." (PMID 31557936, 2019). "Whereas these subclonal mutations may have contributed to tumorigenesis, it is most likely the ubiquitous presence of the mTOR Q2499R mutation that may explain the homogeneity of the histological SEGA-like appearance in this tumor." (PMID 31258848, 2019). "MTOR histological expression is increased in patients with multinodular disease but it is not influenced by other histological features classically associated with worse prognosis such as microvascular invasion or poor tumour differentiation." (PMID 30650598, 2019). "It has been hypothesized that the upregulation of the mTOR pathway would be associated with increased tumour recurrence rates and shorter survival after potentially curative therapies such as surgical resection or LT." (PMID 30650598, 2019).